ZNF284 (zinc finger protein 284)
Description:
May be involved in transcriptional regulation.
Synonyms: ZNF284L; DKFZp781F1775
Tractability: PROTAC: ubiquitination databases record sites on it.
Gene: Protein-coding gene on chromosome 19 (44,072,138 to 44,089,613, forward strand). Ensembl gene ENSG00000186026.
Subcellular location: Nucleus
Gene Ontology:
Molecular function: DNA-binding transcription factor activity, RNA polymerase II-specific; RNA polymerase II cis-regulatory region sequence-specific DNA binding
Biological process: regulation of DNA-templated transcription; negative regulation of transcription by RNA polymerase II
Cellular component: nucleus; nucleoplasm
Genetic constraint (gnomAD): Loss-of-function variants: 12 observed, 13.87 expected, observed/expected ratio (o/e) 0.87, 90% interval 0.55 to 1.4. The upper end of that interval is the gene's LOEUF score, 1.4, which puts it in group 5 of 6, group 1 being the genes least tolerant of losing a copy. Missense variants: 666 observed, 740.11 expected, observed/expected ratio (o/e) 0.9, 90% interval 0.84 to 0.96. Synonymous variants: 225 observed, 250.09 expected, observed/expected ratio (o/e) 0.9, 90% interval 0.81 to 1.
Homologues: Orthologues: chimpanzee ZNF284 (99% identical). Paralogues in human: ZNF225 (77% identical), ZNF224 (71% identical), ZNF221 (60% identical), ZNF235 (44% identical), ZNF227 (42% identical), ZNF658 (41% identical), ZNF229 (41% identical), ZNF226 (41% identical), ZNF28 (41% identical), ZNF33B (41% identical), ZNF841 (40% identical), ZNF41 (40% identical), and 164 more.
Diseases named in the same sentence as ZNF284 in open-access papers:
ZNF284 is named in the same sentence as 1 disease in open-access papers, as found by Europe PMC text mining. Sharing a sentence is not in itself a finding about the gene and the disease. The quoted sentences say what the papers report.
cancer (1 paper, 2020). A tumor composed of atypical neoplastic, often pleomorphic cells that invade other tissues. "However, there are no any reports or laboratory data on the relationship between cancer and the following genes: GSG1L, CRB1, XKR8, ZNF680, ZNF284, and ZNF780B, which is part of the 17-gene signature." (PMID 32596394, 2020). "The other six genes (GSG1 like (GSG1L), crumbs cell polarity complex component 1 (CRB1), XK-related 8 (XKR8), zinc finger protein 680 (ZNF680), zinc finger protein 284 (ZNF284), and zinc finger protein 780B (ZNF780B)) are not mentioned in the cancer research area until now." (PMID 32596394, 2020).